GSN (gelsolin)
Diseases named in the same sentence as GSN in open-access papers (continued):
Sharing a sentence is not in itself a finding about the gene and the disease.
cancer (continued). "Furthermore, Gelsolin and Scinderin expression was assessed in different grades and stages to determine the association of this gene with cancer progression." (PMID 32636728, 2020). "Furthermore, Gelsolin and Scinderin expressions were assessed in different grades and stages to determine the association of this gene with cancer progression." (PMID 32636728, 2020). "Taken together, these data suggest that patients harboring GSN gene defects may increase their susceptibility for developing a cancer as well as they would be more prone to the cancerous effects of the anticancer therapies." (PMID 30925779, 2019). "Resistance to 5-fluorouracil, cisplatin, adriamycin and vinblastine were also reduced in GSNKD cells (Figure 3D1-3D4), corresponding well with previous reports that gelsolin expression was associated with the metastatic potential and anticancer drug resistance of cancer cells." (PMID 29100377, 2017). "The clinical evidence also indicated that the GSN expression may be associated with survival from malignant breast cancers, and the frequency of GSN deficiency increases significantly with progression to invasive phenotypic cancer cells." (PMID 26482896, 2015). "However, there is also evidence that the re-emergence of gelsolin in tumors may promote aggressive behavior, as progressively malignant stages in cancer are associated with high gelsolin expression." (PMID 22927998, 2012). "Enhanced motility, invasiveness, and poor clinical outcomes are commonly linked to altered expression of ABPs, including cofilin, fascin, profilin, gelsolin, and ezrin, which are often dysregulated in malignancies." (PMID 40723199, 2025). "A reduction in gelsolin function can help to stabilize actin structures that facilitate cellular adhesion and migration, allowing cancer cells to spread more easily." (PMID 40723199, 2025). "Our results demonstrate that VDAC1-interacting peptides derived from actin and gelsolin induce cell death and disrupt the actin–gelsolin network, offering a potential strategy for cancer therapy." (PMID 41006687, 2025). "Gelsolin (Gsn Iso-2; an actin regulator that inhibits apoptosis and plays a role in podosome formation) is known to induce cancer cell invasion by altering levels of reactive oxygen species." (PMID 38730628, 2024). "Since current research is limited to a single type of cancer, prognosis, or mechanism, investigating GSN function in a pan-cancer is crucial." (PMID 37035750, 2023). "Most cancers showed hypophosphorylated gelsolin, and in most cancers, the gelsolin promoter was found to be hypermethylated." (PMID 37373424, 2023). "A growing piece of evidence shows the role of GSN in mediating the interplay between cancer cells and TME through the remodeling of the extracellular matrix and selective suppression of immune cells." (PMID 37958747, 2023). "In most cancers, GSN expression was positively connected to the invasion degree of multiple immunological cells, particularly CAFs and mDCs." (PMID 37035750, 2023). "TGF-β1 upregulation can increase GSN expression, inhibit cancer cell growth and progression, as well as promote cancer cell migration." (PMID 37035750, 2023). "In a greatly significant finding, screening research showed gelsolin downregulation in most tumors—and differential expression in differing molecular and immunological cancer types." (PMID 37373424, 2023). "To identify the possible mechanisms for GSN involvement in pan-cancer, we subsequently performed GSEA analysis according to the reactome pathway database." (PMID 37035750, 2023). "KEGG and GSEA analyses showed that GSN was vital in the functions and proteoglycans processes in cancer, chemokine signaling pathway and other immune-related pathways, DNA methylation and cell cycle." (PMID 37035750, 2023). "The findings revealed that GSN expression varied across 33 malignancies, and GSN expression was significantly elevated in 11 cancer forms and reduced significantly in 17 cancer forms." (PMID 37035750, 2023).
cancer (continued). "Accordingly, GSN methylation levels were adversely related to GSN mRNA expression in most cancers except for CHOL and DLBC." (PMID 37035750, 2023). "In conclusion, we inferred that GSN played an essential role in cancer primarily by influencing immune-related pathways and regulating biological functions such as DNA methylation." (PMID 37035750, 2023). "One of the proteins that we discovered to be significantly downregulated in cancer patients compared to healthy controls was gelsolin (GSN)." (PMID 37958747, 2023). "To comprehend if GSN expression influences the outcome of cancer patients, we carried out a survival analysis according to GSN expression in cancer patients using the PrognoScan database." (PMID 37035750, 2023). "GSN expression was positively related to MSI in BLCA, COAD, LUSC, as well as SKCM, whereas GSN was low expressed in these cancers." (PMID 37035750, 2023). "While many studies have examined the function of Gelsolin in the context of cancer, inflammation and amyloidosis, its function during mitosis remains elusive." (PMID 37398341, 2023). "This research mainly investigated the influence of GSN on carcinogenesis and progression and its molecular mechanism, including cancer cell proliferation, metastasis, and the means of GSN-mediated EMT." (PMID 37035750, 2023). "Then, we employed the TISIDB database to investigate the differential expression of GSN in various pan-cancer immunological as well as molecular subtypes." (PMID 37035750, 2023). "KEGG (Kyoto Encyclopedia of Genes and Genomes) and Gene Set Enrichment Analysis (GSEA) analyses showed gelsolin to be vital in cancers for DNA methylation, cell cycle, functions of proteoglycan pathways, chemokine signaling, and immune-related pathways." (PMID 37373424, 2023). "In many cancers, GSN expression was highest in the C3 (inflammatory) immune subtype and lowest in the C4 (lymphocyte-depleted) immune subtype." (PMID 37035750, 2023). "Our study supports these articles, revealing a relationship between poor prognosis and gelsolin overexpression, but gelsolin effect in the process of cancer transformation from precancerous lesions in LSCC has still not been studied." (PMID 34144901, 2022). "The mechanism controlling this apparent dual function for GSN in cancers needs to be explored further in the future." (PMID 35941115, 2022). "The controversial role of GSN has been observed in cancer as both a tumor suppressor gene and oncogene." (PMID 35804959, 2022). "Downregulated GSN leads to increased cell mobility through actin stress filaments, which can promote cancer metastasis." (PMID 35370996, 2022). "In an in vivo cancer model, secreted gelsolin inhibits Clec9a-dependent cross presentation of antigen and dampens CD8+ T cell responses." (PMID 35173718, 2022). "UHRF1 effectively inactivated gelsolin in HeLa cells, whereas thymoquinone induced the expression of gelsolin and promoted apoptotic death in cancer cells." (PMID 35682990, 2022). "Previous studies have shown that GSN expression was decreased in several types of cancers (bladder, breast, lung, and prostate) compared to normal tissues." (PMID 36291171, 2022). "The function of GSN as both a growth inhibitor gene and oncogene depends on the specific carcinoma type through regulation of actin cytoskeleton remodeling and cell motility." (PMID 35941115, 2022). "GSN acting as a growth inhibitor or oncoprotein depends on the specific pathological conditions and carcinoma type." (PMID 35941115, 2022). "Other work in vitro analyzed that the 17AA (-)/KTS (-) WT1 isoform modulates the expression of cytoskeletal regulatory proteins such as α-actinin 1, cofilin, and gelsolin, allowing cancer cells to acquire a more aggressive phenotype." (PMID 34845427, 2021). "As an actin filament-severing and capping protein, it was reported that gelsolin is directly involved in cancer development and progression." (PMID 34947825, 2021).
cancer (continued). "Gelsolin is now being demonstrated to be a multifunctional regulator of cellular signalling, apoptosis, and cancer epithelial mesenchymal transition via mechanisms distinct from those that regulate actin." (PMID 34948078, 2021). "Gelsolin’s effects on actin cytoskeleton are often altered in cancer cells which directly influence cell migration, shape, and growth." (PMID 33171868, 2020). "Gelsolin, an actin-remodeling protein, is involved in cell motility, cytoskeletal remodeling, and cytokinesis and is abnormally expressed in many cancers." (PMID 32992584, 2020). "Among the 17 selected differentially expressed proteins, we selected the 2 with the lowest and highest fold-change (cancer/control), along with gelsolin and contactin-1, which are related to TC, for further validation." (PMID 32704452, 2020). "Gelsolin (GSN), a cytoskeletal protein, is frequently overexpressed in different cancers and promotes cell motility." (PMID 32377190, 2020). "Contradictory results were observed in the current research since suppression of Gelsolin expression correlated with cancer onset, progression, and invasion." (PMID 32636728, 2020). "Down-regulation of gelsolin contributes to the disorganized cytoskeleton present in many cancer cells." (PMID 31413273, 2019). "In particular, GSN has been demonstrated to regulate apoptosis, proliferation as well as metastatic process in several cancers." (PMID 30925779, 2019). "The role of gelsolin in cancer cell biology is not yet clearly understood, as gelsolin has been shown to enhance cell motility when over-expressed and a reduction of gelsolin in some cancer cell lines leads to a decrease in cancer cell invasiveness." (PMID 30506376, 2019). "A few reports suggest the utility of gelsolin in body fluids other than plasma in early cancer detection." (PMID 30149613, 2018). "The role of secreted gelsolin in cancer is still poorly understood, and all statements on predictive value of pGSN in cancers should be treated with caution." (PMID 30149613, 2018). "Currently, the majority of cancer-related studies are focused on the role of cytoplasmic gelsolin; data about the prognostic value of extracellular gelsolin are considerably less abundant." (PMID 30149613, 2018). "The expression of gelsolin (GSN) is abnormal in many cancers, including extranodal nasal-type natural killer/T-cell lymphoma (NKTCL)." (PMID 29175858, 2018). "A previous study revealed that the levels of GSN are decreased in various cancers, including breast, urinary bladder, colon, kidney, ovary, prostate, gastric and urinary system cancer." (PMID 29175858, 2018). "The respective and the joint effects of secreted gelsolin and cancer cells on CD4+ and CD8+ T lymphocytes suggested that surface markers were involved in a cell-to-cell interaction." (PMID 29100377, 2017). "Gelsolin has also been shown to be important for the formation of podosomes in osteoclasts, the equivalent structure of invadpodia in non-cancer cells." (PMID 27391159, 2016). "In conclusion, our study shows a mechanistic insight into the role of gelsolin in cancer cell invasion." (PMID 27391159, 2016). "Our study reveals gelsolin as a novel upstream inducer of O2.- in cancer cells as well as provide evidence to link gelsolin-induced invasion to an increase in intracellular O2.-." (PMID 27391159, 2016). "Our study therefore identified gelsolin as a novel regulator of intracellular O2.- in cancer cells via interacting with Cu/ZnSOD and inhibiting its enzymatic activity." (PMID 27391159, 2016). "Gelsolin (GSN), which functions as a cell growth promotor and apoptosis inhibitor, has been implicated in the oncogenesis of certain cancers." (PMID 27832764, 2016). "Aim of the present work was to investigate the role of the physical interaction between E7 and GSN in an appropriate cancer cell context." (PMID 27072581, 2016).
cancer (continued). "Here, our data show that gelsolin plays a previously unrecognized role in cancer metastasis through inhibition of the PKR-p38 signaling pathway." (PMID 27419625, 2016). "By virtue of these properties, combined with the ability to regulate protease secretion, gelsolin promotes cell invasion and migration in various carcinoma cell types." (PMID 27058427, 2016). "The expression of gelsolin was sensibly reduced both in cancer patients and in healthy carriers compared to controls." (PMID 26061043, 2015). "Low expression of gelsolin has been observed in many cancers, including ovarian, breast, colon and prostate, cervical." (PMID 25393621, 2014). "GSN codes for the actin-binding protein gelsolin, which has multiple cellular functions including apoptosis and is reported to be down-regulated in various cancers and premalignant lesions." (PMID 23675535, 2013). "Loss of GSN expression is detected in UCC and produces changes in cytoskeletal structure typical for cancer." (PMID 22412920, 2012). "This study aims to address the gap in knowledge between gelsolin and the matrix degradation process during cancer cell invasion." (PMID 22927998, 2012). "As a generalization, the gelsolin content of the cells in most cancers is found to be down-regulated, but in a number of studies, researchers found that high gelsolin expression is inversely associated with survival time." (PMID 16882345, 2006). "Gelsolin had been found to suppress tumorigenicity in different cancer samples, including lung, bladder and breast." (PMID 15469618, 2004). "Gelsolin (GSN) is a multifunctional actin-binding protein that plays a pivotal role in regulating cytoskeletal dynamics, cell motility, and apoptosis, thereby exerting significant influence on the progression and prognosis of various cancers." (PMID 40748972, 2025). "These analyses suggesting that GSN might functionally important for cancer progression, immune response and apoptosis process." (PMID 38803199, 2024). "The KEGG pathway analysis revealed that GSN expression is positively related to the pathways in cancer, cell adhesion molecules, chemokine signalling pathway antigen processing and presentation, necroptosis, JAK−STAT signalling pathway and NF‐κB signalling pathway." (PMID 38803199, 2024). "However, many results generated to date are controversial regarding the role of GSN in different carcinomas." (PMID 38803199, 2024). "For kidney cancer, knocking down GSN can inhibit cancer cell proliferation and metastasis." (PMID 37035750, 2023). "In conclusion, the GSN protein exhibited low phosphorylation levels, and the GSN promoter exhibited hypermethylation and affected immune cell invasion and patient outcomes in most cancers." (PMID 37035750, 2023). "The GSN protein was hypophosphorylated, and its promoter was hypermethylated in most cancers." (PMID 37035750, 2023). "Our KEGG analysis showed that GSN might mediate proteoglycans in cancer, PI3K-Akt signaling pathway, endocytosis, leukocyte transendothelial migration, and chemokine signaling pathway." (PMID 37035750, 2023). "In addition, another study showed that cancer cell-secreted gelsolin (GSN) disrupts immunosurveillance by competitively blocking the interaction between extracellular F-actin and DNGR-1 on dendritic cells under ICD stimulation." (PMID 37781042, 2023). "Furthermore, gelsolin was a differentiating prognostic factor for certain specific types of cancers." (PMID 37373424, 2023). "Our analysis included eight cancer types: BLCA, LGG, LUAD, and STAD, whose outcome was positively linked to GSN expression, and CESC, KIRC, SARC, and UCEC, prognosis was negatively correlated with GSN expression." (PMID 37035750, 2023). "In addition, in most cancers, the level of DNA methylation of GSN is negatively correlated with the invasion of immune cells in TME." (PMID 37035750, 2023). "In most cancers, we found differences in GSN expression in various subtypes." (PMID 37035750, 2023).
cancer (continued). "We found that S35 was the most common phosphorylation modification site of GSN in most cancers, but whether it is a functional site needs further research." (PMID 37035750, 2023). "We are the first to examine the involvement of GSN in pan-cancer." (PMID 37035750, 2023). "Therefore, we indirectly explored the level of GSN methylation modification in pan-carcinoma and its role." (PMID 37035750, 2023). "GSN expression is reduced in many transformed and malignant cancer cells, including BC." (PMID 35205837, 2022). "Indeed, GSN knockdown showed an obvious increase of glucose uptake, lactate production, and cell medium acidification in HeLa cells, indicating that GSN knockdown increases glycolytic rate in cancer cells." (PMID 35941115, 2022). "Additionally, increased gelsolin expression, from precancerous lesions to cancer cells, has been reported." (PMID 34144901, 2022). "Growth invasion and migration of cancer cells by GSN and PRDX4 play a more important role in recurrent CRC LNM stage IV than in general stage I, suggesting that GSN and PRDX4 promote cell growth, cell cycle distribution, and motility for the progression of human cancers." (PMID 35804959, 2022). "These different studies show that the role of GSN in cancer depends on the type of cancer studied." (PMID 35178391, 2022). "Gelsolin protein might be considered as a promising molecular marker for prognostic evaluation in human cancer." (PMID 34144901, 2022). "In the same cancers, the expression of the cytoplasmic gelsolin isoform (cGSN) did not correlate with patient survival, highlighting a specific association of sGSN but not cGSN with cancer progression." (PMID 34081922, 2021). "Gelsolin plays a critical role in several diseases, including cardiovascular diseases and cancer." (PMID 34948078, 2021). "The role of GSN in different types of cancer is controversial." (PMID 32377190, 2020). "The expression of gelsolin is frequently reduced in both cancer cell lines and human tumors." (PMID 32704452, 2020). "Cancer cells may evade the apoptosis signaling pathway through Gelsolin down-regulation (Kwiatkowski, 1999)." (PMID 32636728, 2020). "We also studied the molecular mechanisms by which GSN modulates cancer." (PMID 32377190, 2020). "Gelsolin is frequently repressed epigenetically in cancers, and the treatment of HDACi increases gelsolin levels in various cancer cells, suggesting that gelsolin may be a therapeutic strategy in those cancer." (PMID 32992584, 2020). "Studies on the functional and regulatory mechanisms of gelsolin might lead to new possibility to use gelsolin as therapeutic target for cancer." (PMID 33171868, 2020). "Rearrangements of actin filaments are of great importance for both normal cell migration and cancer cell migration/invasion, and indeed, several actin-regulating proteins are implicated in cancer cell migration, two of which are now known to bind CCT: the p21-activating kinase PAK4 and gelsolin." (PMID 30506376, 2019). "Moreover, ATF3 has been determined to bind to the regulatory regions of Gelsolin, resulting in the up-regulation of Gelsolin to prevent cancer cell metastasis." (PMID 29515366, 2018). "Previous studies revealed that the expression of GSN is decreased in many cancers, including NKTCL." (PMID 29175858, 2018). "Because secretion is limited by the pathological conditions, most of the gelsolin could remain inside cancer cells in the transport vesicles." (PMID 29100377, 2017). "Numerous published reports have shown that silencing gelsolin might play a role in cancer development." (PMID 27419625, 2016). "Hence, gelsolin was depleted in several cancer cell lines including HCT116, RKO, Caco-2, DLD-1, HeLa and HepG2 and CM-H2DCFDA oxidation assay was performed." (PMID 27391159, 2016). "Stimulated by these findings, here we hypothesized that gelsolin, a key actin regulatory protein, may contribute to the control of ROS levels in cancer cells." (PMID 27391159, 2016).